CEACAMP7 (CEA cell adhesion molecule pseudogene 7)
Synonyms: CEACAM28P; CGM14
Gene: Unprocessed pseudogene on chromosome 19 (42,949,503 to 42,950,387, reverse strand). Ensembl gene ENSG00000227349.
Diseases named in the same sentence as CEACAMP7 in open-access papers:
CEACAMP7 is named in the same sentence as 1 disease in open-access papers, as found by Europe PMC text mining. Sharing a sentence is not in itself a finding about the gene and the disease.
CEACAMP7 shares sentences with these, for which no sentence is quoted: cancer (1 paper).